MMP13 (matrix metallopeptidase 13)
Diseases named in the same sentence as MMP13 in open-access papers (continued):
Sharing a sentence is not in itself a finding about the gene and the disease.
periodontitis (continued). "Therefore, this higher identifiable activity of MMP-13 in Marfan samples indeed could be associated to the degeneration of soft and hard tissues by pro-MMP-9 activation during progression of chronic periodontitis." (PMID 31340803, 2019). "Metabolism of MMP‐13 may thus have some gender implications in periodontitis." (PMID 29744196, 2017). "Protein–protein interaction (PPI) network analysis identified ESR1, MMP2, MMP9, MMP13, and STAT1 as hub genes, highlighting their central role in EGCG-mediated modulation of periodontitis." (PMID 41009706, 2025). "By integrating these results with Gene Ontology, pathway, and disease enrichment analyses, it was determined that ESR1, MMP2, MMP9, MMP13, and STAT1 are potential key targets of EGCG in the context of periodontitis treatment." (PMID 41009706, 2025). "In patients with moderate to advanced periodontitis, GCF MMP-9 and MMP-13 levels have been shown to be significant predictors of disease progression over a two-month monitoring period." (PMID 41328144, 2025). "Recent evidence highlights several molecular mediators involved in the pathogenesis of periodontitis namely estrogen receptor 1 (ESR1), matrix metalloproteinases (MMP2, MMP9, MMP13), and signal transducer and activator of transcription 1 (STAT1)." (PMID 41009706, 2025). "In the IL-17 Signaling pathway, identified as the most suppressed CP, FOS, JUN, Matrix Metallopeptidase 13 (MMP-13), and C-C Motif Chemokine Ligand 20 (CCL20) were downregulated in periodontitis tissues (Log2FC<-1.5)." (PMID 41124422, 2025). "Among collagenases, MMP-8 accounts for nearly 80% of total collagenase activity in GCF, while MMP-13 and MMP-1 contribute smaller amounts in chronic periodontitis." (PMID 41328144, 2025). "The strong interactions of EGCG with ESR1, MMP2, MMP9, MMP13, and STAT1 support its potential to modulate MMP activity and reduce extracellular matrix degradation, thereby mitigating tissue destruction in periodontitis." (PMID 41009706, 2025). "The authors concluded that several MMPs, particularly MMP-1, MMP-2, MMP-9, and MMP-13, are involved in gingival ECM degradation during periodontitis." (PMID 38474009, 2024). "The immunohistochemically labeled cells for MMP-13 and for MMP-8 were higher in density in periodontitis gingiva when compared with healthy control tissue (p < 0.01)." (PMID 37371608, 2023). "There seems to be a significant increase in MMP expression and activity in chronic periodontitis, especially MMP-1, MMP-3, MMP-7, MMP-8, and MMP-9, with minor contributions from MMP-13 and MMP-14." (PMID 32650590, 2020). "The sensor is sensitive also to cleavages by MMP-1, MMP-13, and MMP-9 present and upregulated in the diseased periodontitis and peri-implantitis tissue and oral fluids." (PMID 30154936, 2018). "Because type I collagen represents the bulk component of periodontal extracellular matrix, special attention has been paid to collagenases—particularly MMP-8 and MMP-13- and gelatinases—MMP-2, and MMP-9- in periodontitis." (PMID 28218665, 2017). "In different sites from the same periodontitis patients (P2: P3, P7: P8, and P9: P10), it was clearly noticeable that MMP3, MMP13, and LBP expressions differ in a site-specific manner." (PMID 27531006, 2016). "Furthermore, lack of association between these variants and periodontitis may also suggest that an increase in the MMP-12 or MMP-13 transcriptions may not necessarily lead to an increase in the destructive effect of these enzymes on the periodontal tissues." (PMID 27194818, 2016). "But MMP‐13 values were significantly higher in the no‐periodontitis group when compared with the periodontitis patients (p = .032)." (PMID 29744196, 2017). "However, Gonçalves and colleagues revealed that MMP transcripts (for MMP-1, MMP-2, MMP-9, and MMP-13) found in gingiva samples were not significantly different in patients affected by gingivitis, chronic periodontitis, and aggressive periodontitis." (PMID 38474009, 2024).
periodontitis (continued). "More recently, MMP‐8 and MMP‐13 in saliva increased with periodontitis disease progression and decreased after its nonsurgical treatment (Ozcan, Saygun, Serdar, Bengi, & Kantarci, 2016), but the concentration ranges were mostly higher for MMP‐13 and much lower for MMP‐8, than here reported." (PMID 29744196, 2017). "We investigated serum and saliva concentrations of matrix metalloproteinases, MMP‐8, MMP‐9, and MMP‐13, and their tissue inhibitor TIMP‐1, in a group of patients with and without periodontitis from Sweden." (PMID 29744196, 2017). "However, in the rat, MMP-13 is analogous to the constitutive collagenase, MMP-1, in humans and likely plays a role in physiologic turnover of collagen rather than the pathological degradation of collagen during periodontitis." (PMID 25104884, 2014).
lung carcinoma (33 papers, 2008 to 2024). "Increased expression of MMP-3 and MMP-13 are associated with the augmentation of cell migration in lung cancer." (PMID 32711573, 2020). "We conducted a meta-analysis, using a comprehensive strategy based on the logistic regression and a model-free approach, to derive a more precise estimation of the relationship between MMP1, MMP2, MMP9 and MMP13 polymorphisms with lung cancer risk." (PMID 26198673, 2015). "In this study we have investigated the effect of polymorphisms in the promoter regions of the three human collagenases (MMP1, MMP8 and MMP13) and the individual risk of developing lung cancer in a group of 501 cases and 510 controls." (PMID 19094243, 2008). "We have investigated the association between three polymorphisms (-1607 1G/2G, +17 C/G and -77 A/G) in the human collagenases MMP1, MMP8 and MMP13 and the risk of development or progression of lung cancer." (PMID 19094243, 2008). "The present study is a case–control study aimed to demonstrate the effects of the association between the MMP9 -1562C/T (rs3918242) and MMP13 -77A/G (rs2252070) gene polymorphisms, alone or under interaction, and the risk of lung cancer in our Chinese Population." (PMID 30889876, 2019). "The A allele and AA genotype of MMP13-77 may protect against lung cancer, and should have an associated with a decreased risk of NSCLC with Southern Chinese people." (PMID 30889876, 2019). "Moreover, the object of carrying MMP9 CC and MMP13 GG genotypes along showed a significantly increased risk of lung cancer (p = 0.00, OR = 5.34, 95% CI = 2.46–11.60) compared with other genotypes." (PMID 30889876, 2019). "Since MMP-13 is often overexpressed in lung cancer and can increase the risk of metastasis, circRNA_100876 might be involved in tumor cell growth, progression, and metastasis in NSCLC, by regulating MMP-13 expression as a miRNA sponge." (PMID 29349062, 2017). "In this study, we reasoned that polymorphisms in the regulatory regions of the three human collagenases (MMP1, MMP8 and MMP13), affecting the expression level of these genes, might influence the risk and survival of lung cancer patients." (PMID 19094243, 2008). "Similarly, the AA genotype of MMP13 might be a marker of decreased serum level of lung cancer, which could decrease the risk of lung cancer and be consistent with the results of the SNP analysis." (PMID 30889876, 2019). "Some studies have found that the C allele of genetic polymorphism in MMP-9 gene rs3918242 was significantly associated with an increased risk for the lung cancer patients, but the details on how genetic variant impacts MMP13 expression is still largely unknown." (PMID 30889876, 2019). "Similarly, the MMP13 AA genotype might be a marker of decreased genotype susceptibility to lung cancer compared with the GG genotype (p = 0.03, OR = 0.56, 95% CI = 0.33–0.94)." (PMID 30889876, 2019). "Other positive hits included MMP13, which is one of three genes recently identified as being drivers of lung cancer brain metastasis." (PMID 38594748, 2024). "Cleavage of SPARC extracellular Ca2+ binding domain by MMP‐8 and MMP‐13 has been detected in the serum of patients with lung cancer, suggesting their presence also in vivo." (PMID 36346290, 2023). "An acidic microenvironment induces MMP2, MMP3, MMP9 and MMP13 expression to promote breast or lung cancer progression." (PMID 35414794, 2022). "It has been revealed that the effects of THBS2 on upregulating MMP-13 and promoting the mobility of lung cancer cells were realized via the integrin αvβ3/FAK/Akt/NF-κB pathway." (PMID 36118676, 2022). "MMP2, MMP9 and MMP13 have been found upregulated and enhance the migration capability of lung cancer cells." (PMID 34820358, 2021). "Good correlations have been observed between levels TSP‐2 and MMP‐2 expression in prostate cancer, and TSP‐2‐induced modulation of MMP‐13 expression in lung cancer cells regulates tumour metastasis." (PMID 33021341, 2020).
lung carcinoma (continued). "In this model, ATM is the key up-steam regulator of TNF-α activated ERK/p38-NF-κB pathway, which play a vital role in promoting lung cancer cell migration by up-regulating MMP-13 expression." (PMID 27556690, 2016). "Together, these results demonstrate that ATM-ERK/p38-NF-κB play important roles in TNF-α up-regulating MMP-13 expression and promoting lung cancer cell migration." (PMID 27556690, 2016). "In the present study, we demonstrated that the activation of ATM-ERK/p38-NF-κB, which induced by TNF-α in autocrine or paracrine manner, up-regulate MMP-13 expression and thereby augment lung cancer metastasis." (PMID 27556690, 2016). "In the present study, we demonstrated that TNF-α promoted lung cancer cell migration by up-regulation of matrix metalloproteinase-13 (MMP-13)." (PMID 27556690, 2016). "Here, we found that TNF-α promote lung cancer metastasis by MMP-13 up-regulation and ATM activation." (PMID 27556690, 2016). "Together, these data demonstrate that MMP-3 and MMP-13 are the key MMPs in IL-6 promoting lung cancer metastasis." (PMID 26528698, 2015). "In the present study, we found that the high IL-6 level reveals both the increased expression of MMP-3/MMP-13 and the enhanced migration abilities of lung cancer cells." (PMID 26528698, 2015). "While expression of MMP-2 and MMP-9 have been characterized extensively in lung cancer, much less is known about MMP-13." (PMID 26193700, 2015). "In the present study, our results reveal that IL-6 inducing ATM phosphorylation increases lung cancer metastasis via up-regulation of MMP-3/MMP-13." (PMID 26528698, 2015). "Most importantly, the in vivo test showed that the inhibition of ATM abrogate the effect of IL-6 on lung cancer metastasis via MMP-3/MMP-13 down-regulation." (PMID 26528698, 2015). "But until now, little is known about the roles of MMP-3 and MMP-13 in IL-6 correlated lung cancer metastasis." (PMID 26528698, 2015). "Then, the inhibition of ATM phosphorylation abolishes IL-6 increased expression of MMP-3/MMP-13, hence abrogates IL-6 correlated lung cancer metastasis both in vitro and in vivo." (PMID 26528698, 2015). "The present study demonstrated that high IL-6 level increases both expressions and activities of MMP-3 and MMP-13, hence augments cell migration abilities of lung cancer." (PMID 26528698, 2015). "In the present study, this model was used to identify MMP-13 as a target for early detection and progression of lung cancer using FMT." (PMID 26193700, 2015). "Contrary to results observed for polymorphisms in MMP1 and MMP13, the polymorphism studied in MMP8 was associated with a reduced individual susceptibility to develop lung cancer in our study." (PMID 19094243, 2008). "Previous reporters have shown that THBS2 could regulate MMP-2 and MMP-13 to promote tumor metastasis of prostate cancer and lung cancer." (PMID 36118676, 2022). "Compared to breast or lung cancer cell lines, MMP13 is highly expressed in CRC cell lines." (PMID 32429645, 2020). "And NFκB/MMP-13 axis contributes to cell migration of lung cancer and glioma." (PMID 32711573, 2020). "Additionally, we studied the role of MMP‐13‐mediated proteolytic generation of this ECM fragment in VM formation in lung cancer using human LCLC tissue samples and cell lines." (PMID 28766880, 2017). "In conclusion, our findings demonstrate that ATM, which could be activated by lung cancer-associated TNF-α, up-regulate MMP-13 expression and thereby augment tumor metastasis." (PMID 27556690, 2016). "Our previous studies showed that MMP-13 mediate IL-6 increasing lung cancer metastasis via ATM activation, therefore, we speculate that MMP-13 might be a critical potential target for TNF-α augmenting lung cancer migration." (PMID 27556690, 2016). "All together, these data suggest that ATM could be activated by the treatment with IL-6, hence increases the expression of MMP-3/MMP-13 and promotes lung cancer metastasis." (PMID 26528698, 2015).
lung carcinoma (continued). "All these findings demonstrate that IL-6 inducing ATM activation increases the expression of MMP-3/MMP-13, augments the abilities of cell migration and promotes lung cancer metastasis, indicating that ATM is a potential target molecule to overcome IL-6 correlated lung cancer metastasis." (PMID 26528698, 2015). "MMP-13 is detected in early pulmonary invasive adenocarcinomas and may be a potential target for molecular imaging of lung cancer." (PMID 26193700, 2015). "As EMT could be affected by the composition and structure of ECM, the findings that ATM phosphorylation increases MMP-3/MMP-13 expression and promotes lung cancer metastasis indicate that the phosphorylation of ATM might be involved in IL-6 promoting EMT." (PMID 26528698, 2015). "Moreover, the inhibition of ATM phosphorylation not only abrogates IL-6 increased, MMP-3/MMP-13 mediated cell migration in vitro, but also suppresses IL-6 correlating lung cancer metastasis in vivo." (PMID 26528698, 2015). "Because of its role in early stage cancer development, and absence in normal tissue, MMP-13 may also be considered in the future as a relevant target for molecular imaging of lung cancer in vivo." (PMID 26193700, 2015). "Our results constitute the first report that analyze this polymorphism in lung cancer and suggest that the -77 A/G polymorphism in MMP13 does not contribute to the susceptibility to develop lung cancer in the Asturian population." (PMID 19094243, 2008). "On the other hand, the studied polymorphisms in the MMP1 and MMP13 genes do not seem to influence the individual risk to develop lung cancer and survival time in our population." (PMID 19094243, 2008). "In conclusion, this work represents the first study in which polymorphisms in this important group of MMPs (MMP1, MMP8 and MMP13) are analyzed together to understand their contribution to lung cancer development and the effect on disease progression and survival in the Caucasian population." (PMID 19094243, 2008). "Similar to the 1G/2G polymorphism in the MMP1 promoter, the MMP13 G/G genotype presented a lack of association with lung cancer risk (adjusted OR = 1.23; 95% CI = 0.72–2.11)." (PMID 19094243, 2008). "Similarly, the AA genotype of MMP13 might be a marker of decreased serum level of lung cancer (OR = 0.76, 95% CI = 0.51–1.14)." (PMID 30889876, 2019). "One study concluded that through the upregulation of MMP-13, TNF-α promotes tumor growth in lung cancer cells." (PMID 33262947, 2020). "Further studies are needed to verify association of rs1799750 in MMP-1, rs243865 in MMP-2, rs11568818 in MMP-7, rs2252070 in MMP-13 and rs28366003 in MT2A with breast, colon and lung cancers." (PMID 32765800, 2020). "MMP‐13 cleaved Ln‐5 into small fragments, thereby abrogating the EGFR signal that disrupts the formation of VM patterns in lung cancer." (PMID 28766880, 2017). "As MMP-13 is closely involved in IL-6 or TNF-α increasing tumor metastasis, we therefore focused on MMP-13 in TNF-α increasing lung cancer cell migration." (PMID 27556690, 2016). "Here, we investigated the role of ATM phosphorylation in IL-6 increasing MMP-3/MMP-13 expression, but the exact mechanism by which MMP-3/MMP-13 promoting lung cancer metastasis is still to be clarified." (PMID 26528698, 2015). "As MMP-3/MMP-13 plays the pivotal roles in TNF-α increased metastasis, we therefore investigated the role of MMP-3/MMP-13 in IL-6 enhanced lung cancer metastasis." (PMID 26528698, 2015). "Meanwhile the distinct role of Kindlin-1 and Kindlin-2 in the regulation of lung cancer cell invasion was examined by determination of the expression of metalloprotenases including MMP7, MMP9 and MMP13." (PMID 23209705, 2012). "Different patient-like orthotopic animal models of lung cancer with GFP-transfected cell lines could be used to track metastatic cells and study the influence of MMP-13 on the metastatic niche." (PMID 26193700, 2015).
lung carcinoma (continued). "MMPs, such as MMP-3, MMP-9, MMP-13 were negative prognostic factors for lung cancer survival." (PMID 27556690, 2016). "For example, Runx2 interaction with p300 alters chromatin structure (acetylation of histones H3 and H4) during activation of MMP-13 gene in bone cell lineage in response to PTH and enhances histone acetylation resulting in increased Snail expression and decreased E-cadherin in lung cancer cells." (PMID 22537242, 2012).